LYRM2 (LYR motif containing 2)
Description:
Involved in efficient integration of the N-module into mitochondrial respiratory chain complex I.
Synonyms: DJ122O8.2
Tractability: PROTAC: ubiquitination databases record sites on it; its protein half-life has been measured.
Gene: Protein-coding gene on chromosome 6 (89,568,144 to 89,638,755, reverse strand). Ensembl gene ENSG00000083099.
Subcellular location: Mitochondrion
Subcellular location (Human Protein Atlas): Cytosol
Pathways (Reactome):
Metabolism: Complex I biogenesis
Gene Ontology:
Molecular function: protein binding
Biological process: mitochondrial respiratory chain complex I assembly
Cellular component: mitochondrion
Genetic constraint (gnomAD): Loss-of-function variants: 7 observed, 9.53 expected, observed/expected ratio (o/e) 0.73, 90% interval 0.42 to 1.37. That is too few expected variants to judge how well the gene tolerates losing a copy. Missense variants: 89 observed, 76.37 expected, observed/expected ratio (o/e) 1.17, 90% interval 0.98 to 1.39. Synonymous variants: 26 observed, 29.28 expected, observed/expected ratio (o/e) 0.89, 90% interval 0.65 to 1.23.
Homologues: Orthologues: macaque LYRM2 (97% identical), dog LYRM2 (95% identical), pig LYRM2 (92% identical), guinea pig LYRM2 (89% identical), mouse Lyrm2 (89% identical), rat Lyrm2 (89% identical), rabbit LYRM2 (67% identical).
Diseases named in the same sentence as LYRM2 in open-access papers:
LYRM2 is named in the same sentence as 5 diseases in open-access papers, as found by Europe PMC text mining. Sharing a sentence is not in itself a finding about the gene and the disease. The quoted sentences say what the papers report.
colorectal cancer (3 papers, 2021 to 2025). A primary or metastatic malignant neoplasm that affects the colon or rectum. "Localized within the inner mitochondrial membrane and matrix, LYRM2 directly interacts with complex I of the electron transport chain, enhancing its activity and driving oxidative phosphorylation in colorectal cancer cells." (PMID 39886381, 2025). "LYRM2 is upregulated in colorectal cancer, where it promotes tumor growth both in vivo and in vitro." (PMID 39886381, 2025). "Previous study demonstrated that LYRM2 expression is increased in colorectal cancer, where it promotes the growth of cancer cells." (PMID 39661026, 2024). "LYR motif containing 2 (LYRM2) has been identified as an oncogene in colorectal cancer; however, its expression, functions and molecular mechanism in the context of HCC has not been investigated." (PMID 39661026, 2024). "In colorectal cancer, LYRM2 has been shown to promote the oxidative phosphorylation and the growth of cancer cells through its interaction with mitochondrial complex I." (PMID 39661026, 2024). "Notably, in the context of colorectal cancer, LYRM2 has been shown to promote OXPHOS of colorectal cancer cells." (PMID 39661026, 2024).
tumor (2 papers, 2024 to 2025). "IHC staining of subcutaneous tumour tissues indicated that the protein level of HIF‐1α was reduced in the LYRM2 konckdown group." (PMID 39661026, 2024). "Mechanistically, LYRM2 exerts its tumour‐promoting effects in HCC by enhancing glycolysis while inhibiting the mitochondrial respiration." (PMID 39661026, 2024). "In the subcutaneous xenograft models, the volume of subcutaneous tumours formed in the LYRM2 knockdown group was significantly smaller compared to the control group." (PMID 39661026, 2024). "Additionally, IHC staining demonstrated LYRM2 knockdown resulted in an increased level of E‐cadherin, while decreasing the expression of N‐cadherin and vimentin in the tumour tissues." (PMID 39661026, 2024). "Second, the tumour microenvironment (e.g., hypoxia) may induce the expression of LYRM2 in HCC cells in control group during the process of in vivo growth and metastasis, potentially diminishing the effects of LYRM2 overexpression." (PMID 39661026, 2024). "Additionally, Ki‐67 and IHC staining for E‐cadherin, N‐cadherin and Vimentin in xenograft tumours revealed that the suppression of LYRM2 in HCC cells inhibited both the cell proliferation and EMT." (PMID 39661026, 2024). "Furthermore, elevated LYRM2 levels were correlated with more advanced tumour grade and tumour stage in HCC patients, based on the data mining in TCGA database." (PMID 39661026, 2024). "LYRM2 expression level was elevated in HCC tissues compared to adjacent non‐tumour liver tissues." (PMID 39661026, 2024). "However, it is noteworthy that the overexpression of LYRM2 did no significantly enhance tumour growth and metastasis in vivo (data not shown)." (PMID 39661026, 2024).
cancer (1 paper, 2024). A tumor composed of atypical neoplastic, often pleomorphic cells that invade other tissues. "Given EMT is associated with the enhanced metastatic capacities of cancer cells, we further explored whether LYRM2 affects the EMT process in HCC cells." (PMID 39661026, 2024). "Next, we investigated the role of LYRM2 in the metabolic reprogramming of HCC cells, given the increased glycolysis in cancer cells is a well‐recognised hallmark responsible for malignant growth and metastasis." (PMID 39661026, 2024). "Given that EMT is an important reason for the enhanced cell metastasis, we checked the role of LYRM2 in the EMT process of cancer cells." (PMID 39661026, 2024). "These indicate the influence of LYRM2 on cancer cell metabolism is dependent on the specific cancer type." (PMID 39661026, 2024). "This suggests that the activation of the AKT is responsible for the promoting effects of LYRM2 on cancer growth and metastasis." (PMID 39661026, 2024). "Currently, the understanding of LYRM2, particularly regarding its role in human cancers, is limited." (PMID 39661026, 2024).
LYRM2 also shares sentences with these, for which no sentence is quoted: hepatocellular carcinoma (1 paper); liver cirrhosis (1).